SNORA69 (small nucleolar RNA, H/ACA box 69)
Synonyms: U69; RNU69; U69A
Gene: Small nucleolar RNA gene on chromosome X (119,787,353 to 119,787,484, reverse strand). Ensembl gene ENSG00000206622.
Gene Ontology:
Biological process: RNA processing
Cellular component: nucleolus
Homologues: Orthologues: chimpanzee SNORA69 (100% identical), macaque SNORA69 (99% identical), pig SNORA69 (92% identical), rat LOC120099449 (80% identical), rat Snora69 (80% identical), mouse Gm22784 (77% identical).
Diseases named in the same sentence as SNORA69 in open-access papers:
SNORA69 is named in the same sentence as 1 disease in open-access papers, as found by Europe PMC text mining. Sharing a sentence is not in itself a finding about the gene and the disease. The quoted sentences say what the papers report.
depression (1 paper, 2024). "We further investigated the expression of Snora69 in the LHb and peripheral blood of an unpredicted chronic mild stress (UCMS) mouse model of depression." (PMID 38589409, 2024).